MIR3929 (microRNA 3929)
Synonyms: hsa-mir-3929
Gene: MicroRNA gene on chromosome 18 (35,934,088 to 35,934,142, reverse strand). Ensembl gene ENSG00000265641.
Homologues: Orthologues: chimpanzee MIR3929 (100% identical).